TNF (tumor necrosis factor)
Diseases named in the same sentence as TNF in open-access papers (continued):
Sharing a sentence is not in itself a finding about the gene and the disease.
infection (continued). "As expected, all infections resulted in a significant increase in pro-inflammatory status as evidenced by increased expression of iNOS, IL-6, and TNF-α." (PMID 32370298, 2020). "At 2 weeks post infection, TNF-α and IL-1β levels were much lower compared to 1-week post infection." (PMID 32958779, 2020). "Cytomegalovirus-infected cells produced TNF-α in response to infection, likely via innate immune signaling; this cytokine induced apoptosis in uninfected cells through paracrine-mediated effects." (PMID 33374185, 2020). "Since macrophages are the predominant host cells of many of those infections, this cell type and the role of TNF in its differentiation will be discussed in particular." (PMID 32760383, 2020). "S aureus has been reported to elicit a subtle immune reaction in the host after infection, through several mechanisms that include attenuation of NF-κB activation in mammary epithelial cells and TNFα, IL-6 and IL-8 in the mammary gland." (PMID 32071371, 2020). "A second wave of TNF-α accumulates between 4 and 8 days post-infection, concurring with the duration of the ADA and ETA treatment." (PMID 32069329, 2020). "In the P-EOW group, the TNF-α production remained at very similar levels at all detection times compared to the healthy control groups in despite of the infection as seen in the W/O-T group, which showed a significant decrease (p = 0.038) at 60 dpi." (PMID 33238401, 2020). "To further study the effect of PKK depletion on lung inflammation after infection, we measured the levels of cytokines (TNFα, IL‐1β, IL‐6) and chemokines (CXCL1, CXCL2) in lung homogenates." (PMID 31595971, 2020). "TNF-α is a cytokine produced in response to infection and is closely related to the NF-κB pathway in the inflammatory response." (PMID 32545418, 2020). "Six hours post-infection, TNF-α mRNA levels were upregulated (2 log10) in A549 cells infected with C4BP treated H1N1 or H3N2, while at the earlier 2-h time point a slight upregulation was observed." (PMID 33488586, 2020). "TNF-α concentration increases fast in 2 to 4 h in both infection and inflammation, having a sensitivity of 75%, specificity of 88%, PPV of 67% and NPV of 51% for 130 ng/mL as the cut-off value." (PMID 33419284, 2020). "The production of IL-6 and TNF-α increased at 16 h (16.05% ± 2.51% and 15.17% ± 1.21%, respectively), but declined at 20 h post-infection (5.87% ± 0.64% and 7.92% ± 0.88%, respectively)." (PMID 33261178, 2020). "Using a chimeric Vi antigen insert into S. Typhimurium, this latter study showed that infection in mice not only inhibited TNF-α and CXCL2 but also increased anti-inflammatory IL-10 production." (PMID 33076485, 2020). "On the other hand, CD4+CD44+IFN-γ+IL-17+IL-2+ T-cells (R = −0.7133, p < 0.0001) and CD4+CD44+IFN-γ+TNF-α+IL-2+ T-cells (R = −0.6845, p < 0.0001) showed correlation with bacterial load only post-infection." (PMID 32545304, 2020). "At 12 h post-infection with the virus, IL-6 and TNF-α were detectable in BMMCs (4.90% ± 0.67% and 10.4% ± 0.66%, respectively)." (PMID 33261178, 2020). "Overall, resistant C3H/He mice express lower cytokine levels than susceptible C57BL/10 mice, with the exception of TNF-α in the footpad and TNF-α, TGF-β, IL-12, and IFN-γ in the spleen, all in the early phase of infection." (PMID 32983013, 2020). "Treatment with celecoxib reduced Mtb CFU in a dose-dependent manner across the conditions including infection alone or when treated with IFNγ, TNFα, or MK571." (PMID 32546788, 2020). "Infected isotype control mice reduced their average food intake between days 1 and 2 of infection, whereas blocking TNF-α prevented inappetence during the early stages of infection (days 1 to 4)." (PMID 32071269, 2020). "NFκB activation is induced by infection, necrotic cell products, oxidative stress, and inflammatory cytokines such as TNF and IL-143." (PMID 32587777, 2020).
infection (continued). "Our experiments demonstrating increased FX activation on EC membranes following exposure to TNF provide additional insight into basic mechanisms of disseminated intravascular coagulation during infection." (PMID 32029851, 2020). "Further, androgenized mice exhibited decreased local IFNγ and TNFα along with increased CXCL1 and G-CSF, associated with decreased local M1:M2 macrophage ratios throughout infection." (PMID 32849562, 2020). "We found that the expression of CCL2, CCL5, IL-6, and TNF-α was inhibited through the course of infection in U0126-pretreated cells and that viral RNA abundance was also decreased in U0126-pretreated cells." (PMID 31694957, 2020). "TNF-α activates macrophages, recruits them to the site of infection, and participates in granuloma formation." (PMID 32457723, 2020). "It is considered one of the most important cytokines during an infection, along with tumor necrosis factor alpha (TNF-α)." (PMID 33244370, 2020). "In the spleens of IM-immunized mice, the frequencies of CD4+ T cells expressing IL-17A, IFN-γ, IL-10 and TNF-α were found similar when compared to controls, both before and after infection." (PMID 32040500, 2020). "We previously reported a role for Blimp-1 in inducing IL-10 production by Th1 cells to become type 1 regulatory T (Tr1) cells that protected against IFNγ- and TNF-mediated splenic pathology during infection." (PMID 33049000, 2020). "Severe systemic inflammation upon infection leads to the production of excessive pro-inflammatory cytokines like IL-6, IFNγ, and TNFα." (PMID 33182754, 2020). "This is the first report that shows the gene polymorphisms of TNF-α − 308 G/A and IFN-γ + 874 A/T in Saudi patients with different L. species infections." (PMID 32404058, 2020). "The in vitro study of EGYVIR extract against SARS-CoV-2 on Huh-7 cell lines, revealed the potential role of NF-kβ/TNFα/IL-6 during the infection process." (PMID 33206688, 2020). "TNF-α is one of the major cytokines involved in lung granuloma formation during the later stages of infection." (PMID 33042856, 2020). "TNF and IL-1β both activate endothelial cells and attract circulating polymorphonuclear white blood cells (PMNs) to the infection site." (PMID 32133014, 2020). "To determine the time point of bacterial killing and TNF-α release more precisely, we performed a kinetic analysis in whole blood in 30 min intervals after in vitro infection with wt S. suis strain 10 (2 × 106 cfu/mL)." (PMID 31947746, 2020). "A cohort study revealed that heterozygosity for S180L confer increased resistance to infection, which was found associated with a low level of IL-6, COX-2, TNF-α, and IL-1β production." (PMID 33072109, 2020). "TNF-α levels were lower in Ly6B.2+ cells from IL-27Rα−/− pups during in vitro infection and marginally higher in BMDMs at 6 h only." (PMID 31818960, 2020). "TNF-α promoted the proliferation, migration, and tube formation in HUVECs, but these effects were attenuated by infection with Ad-CAST." (PMID 32665543, 2020). "There were significant reductions in IL-8, IL-6, and TNF-α production during infection in CFTR KO MDMs when compared to media alone or empty vector transfection." (PMID 32973772, 2020). "In contrast, 36 days after infection, more than 3 weeks after parasite clearance, IL-6 and TNF-α production was significantly increased upon stimulation with LPS, C. albicans and S. aureus compared to baseline." (PMID 33324683, 2020). "In vitro studies with murine macrophages resembling early stages of infection, show that TNF-α-mediated iNOS and ROS induction significantly decreases M. tuberculosis growth." (PMID 32849525, 2020). "Synthesis of interleukins (ILs) and tumor necrosis factor α (TNF-α) from the macrophage in response to infection and inflammatory conditions; stimulate the production of APPs from the liver cell (Jain, Gautam & Naseem, 2011)." (PMID 33240679, 2020).
infection (continued). "The release of pro-inflammatory cytokines was determined in BAL samples collected at day 7 after infection, and concentrations of IL-1β, IL-6 and TNF-α were determined by multiplex immunoassay." (PMID 32899224, 2020). "Their resilience against infection, their major contribution of type I IFNs, the secretion of adequate amounts of TNF-α and IL-6, and the recruitment of NK cells to the lungs are key for the early control of infection." (PMID 32545470, 2020). "In an experimental infection of mice which were deficient in CD4+ Th1 cytokines, IL-12, IFN-γ, TNF-α, or inducible NOS (iNOS) revealed failure to control parasite replication." (PMID 32656269, 2020). "In a mouse model of 2009 H1N1 pandemic influenza, the S1p1 receptor agonist significantly inhibited synthesis of IL-1α, IL-1β, IL-6, IL-10, MCP-1, TNF-α, and GM-CSF, and reduced deaths from lethal infections by more than 80%." (PMID 32574268, 2020). "At 24 h post-infection time, the transcriptional gene expression levels of TNF-α and MLKL were significantly increased by 5.65 ± 0.24 and 1.90 ± 0.38 times (p<0.01; p<0.05), respectively." (PMID 33176697, 2020). "The mRNA expression of the pro-inflammatory cytokines IL-1β, IL-8, and TNF-α, as well as the anti-inflammatory cytokine IL-10 were quantified by qRT-PCR after infection of THP-1 macrophages with the various mycobacteria for 18 h." (PMID 32117140, 2020). "Tumor necrosis factor-α and other immunomodulatory molecules were released as a response to the infection." (PMID 32160882, 2020). "Cell-mediated immunity governed by cytokines such as IFN-γ and TNF-α are mainly responsible to inhibit the growth of M. tb and clear the infection." (PMID 32793184, 2020). "As expected, mice with complete TNF ablation succumbed to the infection as previously shown, but BTNF-/- mice in this study exhibited moderate bacterial burden and inflammatory response compared with TNFf/f mice." (PMID 32742607, 2020). "This dual role of TNF-α suggests that the regulation and time production of pro-inflammatory cytokines are essential to infection control." (PMID 32576141, 2020). "Here, the serum TNF-α levels in mice immunized with C-OPSBa were significantly lower than those in the other treatment groups after infection with B. abortus." (PMID 32244903, 2020). "Increased U frequency in the SARS-CoV-2 genome enhances TNF-α and IL-6 production in our pseudo-infection model." (PMID 33082451, 2020). "A more recent study revealed that Card9−/− mice exhibited impaired local cytokine production (IL-17, IFN-γ, and TNF-α) and Th1 cell response to R. arrhizus in a murine infection model." (PMID 32957440, 2020). "After 30 days of infection, both infected mouse strains showed an upregulation of TNF-α, IL-12, and TGF-β, but IL-12 and TGF-β upregulation was higher in C57BL/10 mice compared to C3H/He mice." (PMID 32983013, 2020). "IFN-γ and TNF-α are cytokines possessing antitumor and immunomodulatory properties and are essential for host immune responses against infection or tissue injury." (PMID 32869156, 2020). "Nonetheless, a side-by-side comparison of the effects of anti-IL-17A or anti-TNF-α neutralizing antibodies in a murine infection model, confirmed the importance of TNF-α in the immune response against Mtb, in contrast to the IL-17 pathway." (PMID 32069329, 2020). "A systemic infection (intraperitoneally) with a suilysin-positive virulent serotype 2 strain in CD1 mice led to a detectable TNF-α increase in serum between 3 and 6 h, but to a decline at 6 h, similar to TNF-α levels before infection." (PMID 31947746, 2020). "We here confirmed that both, TNFα and IL-6 were markedly increased in CIA mice after infection and this was accompanied by severe bone loss within a few days of SA progression." (PMID 33117382, 2020). "ILC1s are able to secrete IFN-γ and TNF upon activation, thereby controlling infections by intracellular bacteria and viruses, and they can express T-bet, the TH1 hallmark transcription factor." (PMID 32545470, 2020).
infection (continued). "In human studies of 2009 pH1N1 infection, TNF-α levels were higher in hospitalized patients than mild cases." (PMID 32974217, 2020). "In line with that, immune CD4+ T cells act on MΦ in the infection with R. typhi and activate the bactericidal activity of these cells via the release of IFNγ and TNFα." (PMID 33091016, 2020). "vICA restrains death-associated inflammatory signaling in myeloid cells such that ∆M36 infection exhibited elevated levels of TNF production or processing of inflammatory cytokine IL-1β when compared to K181." (PMID 33126536, 2020). "This is likely a result of increasing concentrations of pyrogenic pro-inflammatory cytokines, such as TNF-α, IL-1, and IL-6, which affect the thermoregulatory centers of the brain in response to an infection." (PMID 33123678, 2020). "Larvae that had recruitment of macrophages to the site of infection had significant increases for TNFα, interleukin-1-beta (IL1β), and interleukin-6 (IL-6), and this increase in expression in recruited larvae was independent of dissemination." (PMID 32776983, 2020). "It had been reported that the expression of inflammatory cytokine genes like TNFα, IL-1β, IL-6 and IL-8 were up-regulated by the infection of Ich in rainbow trout larvae." (PMID 32295151, 2020). "The frequency of BMMCs producing IL-6 and TNF-α decreased between 16 and 20 h post-infection in IFNAR-intact cells from 16.05% ± 2.51% and 15% ± 1.21% to 5.87% ± 0.64% and 7.92% ± 0.88%, respectively." (PMID 33261178, 2020). "After infection with Penicillium marneffei, the body produces an important defence mechanism that induces TNF‐α production via extracellular signal‐regulated kinase (ERK) 1/2 to resist Pseudomonas marneffei." (PMID 32924263, 2020). "In paw tissue from infected mice after infection, we found a significantly increased level of the principal proinflammatory cytokines IL-1β, IL-6, and TNF-α, while treatment with artesunate significantly reduced the levels of these cytokines." (PMID 32230725, 2020). "The major cellular source of TNF are macrophages and immune cells that are activated in response to infections or tissue damage." (PMID 32528961, 2020). "In corroboration, IAP supplementation significantly reduced systemic endotoxin levels and inflammation after burn site infection injury, as measured by serum LPS and TNF-α levels, respectively." (PMID 33004693, 2020). "Tumor necrosis factor-α (TNF-α) is a potent pro-inflammatory mediator produced by macrophages upon infection to enhance host defense." (PMID 33520735, 2020). "TNF-α mRNA level in PRRSV-infected cells was significantly upregulated at any time point post-infection, compared to mock cells." (PMID 32046249, 2020). "To confirm an increased pro-inflammatory status of the human lung epithelial cells upon super-infection, we analyzed the mRNA expression of different representative pro-inflammatory cytokines and chemokines (IL-6, IL-8, TNFα, IL-1β, and IFN-γ) in detail." (PMID 33333815, 2020). "This contrasted with the non-ST5 infections, in which the mean TNF-α levels had increased from 3256.25 pg/g to 6378.76 pg/g (P = .02) over this same period." (PMID 32196550, 2020). "TNF-α is an endogenous alarm signal, which coordinates gene expression and cellular activity and drives inflammatory responses in injury or infection." (PMID 32117243, 2020). "Both of these proteins are able to partly inhibit hRSV-mediated and TNF-α-mediated cellular apoptosis in the early stages of infection." (PMID 32545470, 2020). "The signaling induced by many of the inflammatory cytokines produced during infection, including TNFα, IL-6, IL-1β, and IL-17A, share much in common with RANKL, including NF-κB and MAPKs." (PMID 32987689, 2020). "The tat induces the expression of monocyte chemoattractant protein-1 (MCP-1), which attracts monocytes to the site of infection and induces the synthesis of tumor necrosis factor alpha (TNF-α), nuclear factor kappa- B (NF-κB) and interleukin-6 (IL-6)." (PMID 32722629, 2020).
infection (continued). "infantum drug combination, as well as inducer of proinflammatory response, as demonstrated by decreased infection and increased TNF-α production." (PMID 33202979, 2020). "To further characterize the treatment-induced immunostimulatory effects, we determined the mRNA levels of the infection-relevant cytokines IL-4 and TNF-α." (PMID 32393489, 2020). "The expression level of tumor necrosis factor-α was unchanged at 24 weeks post infection in both WT and MRP14KO mice." (PMID 31961866, 2020). "All of these chemokines/cytokines were overexpressed after USUV infection whereas IFNβ and TNFα (tumor necrosis factor) levels remained unchanged." (PMID 32324736, 2020). "Ms_YrbE3A induced IL-6 and TNF-α expression in RAW264.7 at various time points starting from 2 h after infection." (PMID 32316659, 2020). "TNF-α triggers cytotoxic T cells to directly kill intracellular pathogen, and recruits monocytes and circulate antigen-specific T lymphocytes to the infection site." (PMID 33117374, 2020). "The physically normal IL-6 and TNF-α levels in the blood of healthy people have the effects of anti-infection and immune function enhancement, but too much of them can damage the tissue." (PMID 32089647, 2020). "The levels of inflammatory cytokines of IL-6 and TNF-α and infection-related biomarker of SF were also significantly increased with the disease progression (P = 0.038, 0.048 and 0.022, respectively)." (PMID 32841294, 2020). "Upon infection, TNF-α, IL-4, and IL-6 expressions heightened, while IL-3 and IL-1β only appeared in trace amounts." (PMID 32943637, 2020). "On day 42 of infection, the concentration of IL-6, TNF, IL-12p40 and IFNγ were significantly reduced in doramapimod-treated animals (white and black bars)." (PMID 32788581, 2020). "When compared to their untreated counterparts, the cells infected with either C4BP treated H1N1 or H3N2 were found to upregulate TNF-α mRNA, indicating a robust inflammatory response at both 2 h (0.2 log10) and 6 h (~1.7 log10) post-infection." (PMID 33488586, 2020). "In contrast, plasmablasts number was significantly higher in the TNF-/- at week 2 after infection and thereafter significantly decreased at week 3 after infection when compared with TNFf/f and BTNF-/- mice." (PMID 32742607, 2020). "Given the relatively long half-lives of most TNF blockers relative to antibiotics, there is concern over sudden stoppage of all treatment by patients, resulting in the unopposed anti-TNF activity and possible worsening of infection." (PMID 33552087, 2020). "During injury or infection, archetypal pro-inflammatory cytokines (IL-1 and TNF-α) are rapidly released." (PMID 33324697, 2020). "The TNF-α mRNA level in PRRSV-infected cells pretreated with anti-FcγRI IgG or anti-FcγRIII IgG was significantly downregulated at any time point post-infection, compared to PRRSV-infected-cells pretreated with RNI." (PMID 32046249, 2020). "The expression of MHC II, CD40, and CD86 in Fo B cells and plasmablasts was significantly decreased in TNF-/- mice at week 3 after infection." (PMID 32742607, 2020). "Incubation with GAS also induced significant release of TNF-α from neutrophils at 180 min (p<0.001) and 360 min (p<0.0001), with significantly greater release during 5448 infection compared to 5448AP at 360 min (p<0.0001)." (PMID 33585270, 2020). "The cell-free supernatants after post-infection were analysed for the expression of pro-inflammatory cytokines IL-1β, IL-6 and TNF-α and anti-inflammatory cytokines IL-10, IL-12p40, IL-12p70 and IL-4." (PMID 32295519, 2020). "Although not statistically different from the matched control, the average amount of TNF-α at 12 hours post-infection was roughly equivalent between loops inoculated with the C. jejuni wild-type strain and the ∆ciaD mutant." (PMID 32887530, 2020).